TH (tyrosine hydroxylase)
Diseases named in the same sentence as TH in open-access papers (continued):
Sharing a sentence is not in itself a finding about the gene and the disease.
depression (38 papers, 2014 to 2026). "Dysregulation of serotonin and dopamine metabolism, mediated by disruptions in the tryptophan-kynurenine pathway and tyrosine hydroxylase (TH) activity, contributes to neurotransmitter imbalances associated with depression." (PMID 40126810, 2025). "Here, it is shown that activation of tyrosine hydroxylase (TH) neurons in the LC alleviates depression‐like behaviors in susceptible mice." (PMID 38155473, 2024). "A loss of dopaminergic proteins was seen in DLB cases with depression compared to controls, including DAT, TH and DDC." (PMID 40113786, 2025). "Here we show that tyrosine hydroxylase expression in the fracture hematoma of patients correlates positively with acknowledged stress, depression, and pain scores as well as individual ratings of healing-impairment and pain-perception post-fracture." (PMID 37277336, 2023). "And tyrosine can be further metabolized by tyrosine hydroxylase to a precursor of catecholamine neurotransmitter, which is closely related to depression." (PMID 35462900, 2022). "According to a previous report, ZPG up regulates the gene expression of dopamine D2 receptors in rats and selective D2 dopamine receptor agonists relieve depression in stressed rats by up-regulating tyrosine hydroxylase." (PMID 35962349, 2022). "Tyrosine can be further metabolized into catecholamine neurotransmitters, such as DA and NE, by TH, which are closely related to depression." (PMID 32265710, 2020). "Our results in this study demonstrated that the TH+ projection of LC neurons to the CA1 region is a functional efferent target for depression-induced aggravated responses to TGI." (PMID 31270312, 2019). "Together, these results suggest that nasal PM2.5 exposure induces depressive-like behaviors through suppression of hypothalamic TH, potentially leading to diminished dopamine synthesis and contributing to mechanisms underlying PM2.5’s impact on major depressive disorder." (PMID 39769289, 2024). "In our study, the maternal methyl-enriched diet increased the expression of the TH gene in the nucleus accumbens and rescued depression-like behaviour (reduced the duration of immobility, increased the duration of climbing and sucrose intake/preference) in adult offspring of WAG/Rij rats." (PMID 36766503, 2023). "This study aimed to investigate whether the maternal methyl-enriched diet (MED), which affects DNA methylation, can alter DNMT1, HCN1, and TH gene expression and modify absence seizures and comorbid depression in WAG/Rij offspring." (PMID 36766503, 2023). "Furthermore, decreased renal tissue norepinephrine concentration, together with the lower expression of TH in the 300, 250, and 200 W groups demonstrated effective sympathetic depression following sufficient deposition of acoustic energy." (PMID 34722673, 2021). "In an animal model of depression, chronic delivery of (Fucus vesiculosus) fucoidan inhibited clinical signs, blocked the increase in tyrosine hydroxylase expression in the localized areas of the brain and inhibited the decrease in BDNF mRNA expression in the hippocampus." (PMID 32121066, 2020). "Numerous studies have demonstrated that the efferent projections of the LC are broad, while the TH+ axonal projections of the LC in depression remain largely unknown." (PMID 31270312, 2019). "In addition, we demonstrate that selective chemogenetic inhibition of TH+ projections from the LC to the CA1 served to mimic depression-like behaviours and induce a worsening response to TGI, further confirming the necessity of this pathway." (PMID 31270312, 2019). "Major depressive disorder may also occur due to a dysfunctional central noradrenergic system manifested by the decreased synthesis of NA, the reduced density of its transporter in the locus coeruleus, and heightened tyrosine hydroxylase activity among individuals with depression." (PMID 38613110, 2024).
depression (continued). "This study also provided new data on the adrenal medulla response to chronic stress since CUMS reduced the catecholamine synthetic capacity of TH in the adrenal glands, which may be responsible for the blunted sympathoadrenal response to acute stress seen in anxiety disorders and depression." (PMID 37834073, 2023). "Immunofluorescence also verified the elevated expression of GAP43 and TH in CUS, suggesting autonomic dysfunction in the CUS-induced rat model of depression." (PMID 38261756, 2024). "This implies that increased expression of the TH gene in the nucleus accumbens as well as increased dopaminergic tone of the mesolimbic brain system may contribute to the suppression of absence seizures and depression-like comorbidity in the offspring of WAG/Rij rats." (PMID 36766503, 2023). "This study investigated the effects of essential oil from Asarum heterotropoides (EOAH) on depression-like behaviors and brain expressions of CRF, 5-HT, and TH in mice challenged with stress." (PMID 25881143, 2015). "Similarly, FEW has been demonstrated to reduce the levels of NE, corticotropin-releasing factor (CRF) and tyrosine hydroxylase, were also discovered after the treatment of FEW in serum in locus coeruleus in a rat model of depression." (PMID 37521479, 2023). "For example, Wilson and colleagues reported lower density tyrosine hydroxylase in the VTA in the postmortem brains of patients with late life depression but not in the DRN or locus coeruleus." (PMID 29867598, 2018). "Based on a role for endogenous systems of CRF, 5-HT, and NE in the brain, one possible mechanism where EOAH could diminish depression-like behaviors is by affecting brain levels of 5-HT, CRF, and TH." (PMID 25881143, 2015). "Similarly, reduced HRV and increased expression of GAP43 and TH were also found in CUS-induced mice, whereas P2X7R-KO significantly mitigated these indicators, validating the dysfunction of ANS in depression and the protective effects of P2X7R in regulating ANS." (PMID 38261756, 2024).
Dystonia (34 papers, 2010 to 2025). An abnormally increased muscular tone that causes fixed abnormal postures. "α-MT is an orally competitive TH inhibitor, which has been used clinically to treat hypertension-linked pheochromocytoma and dystonia, dyskinesia and Huntington's disease." (PMID 36409355, 2022). "In the largest published study of 36 patients with TH mutations, the phenotype was classified into two major types: type A: progressive hypokinetic-rigid syndrome with dystonia; and type B: complex encephalopathy." (PMID 32185155, 2020). "The clinical targeted next generation epilepsy panels include PDE-ALDH7A1, PNPO and GLUT1 deficiencies and dystonia panels include TH, GTPCH, GLUT1, SR and dopamine transporter deficiencies." (PMID 25758715, 2015). "In PD patients, rare large genomic duplications or deletions have also been observed in the PD genes SNCA (PARK1), Parkin (PARK2), and DJ1 (PARK7) and in a gene that causes dystonia/infantile parkinsonism, tyrosine hydroxylase (TH)." (PMID 24073418, 2013). "Missense mutation in both alleles of the TH gene is known to cause dopamine-related phenotypes, including dystonia and infantile Parkinsonism." (PMID 20809526, 2010). "The decrease in dopamine caused by tyrosine hydroxylase (TH) gene mutation may lead to dystonia, tremor and severe encephalopathy in children." (PMID 36568392, 2022). "Although the clinical picture correlates better with TH deficient dopa-responsive dystonia, due to limited time and broad variation of the clinical phenotype, Next Generation Sequencing (NGS) was chosen as the method of analysis for both possibly involved genes." (PMID 30894892, 2018). "Our study shows that mutation of the TH gene may affect the downstream production of dopamine and catecholamine by changing protein structure, function, and enzyme activity; overall, this may lead to dopa-responsive dystonia." (PMID 36568392, 2022). "In addition to DYT5, the enzymatic defects in the dopamine biosynthetic pathway also cause dystonia [i.e., 6-pyruvoyltetrahydropterin synthase, sepiapterin reductase, dihydropteridine reductase, tyrosine hydroxylase (TH), and aromatic L-amino acid decarboxylase (AADC)]." (PMID 34867735, 2021). "Dopa‐responsive dystonia (DRD) encompasses a spectrum of rare, genetically and clinically diverse monogenic dystonias caused by variants in GCH1, TH, SPR, PTS, and QDPR genes." (PMID 40146714, 2025). "In a model of dopa-responsive dystonia, it was found that tyrosine hydroxylase (TH) content was more depleted in the striosome, accounting for the imbalance between the compartments causing dystonia." (PMID 36090883, 2022). "Several previous studies have found that patients carrying mutations in dystonia-related genes, such as GCH1 and TH, displayed features of Parkinsonism in addition to dystonia." (PMID 33964895, 2021). "Other genes found to be associated with isolated or combined dystonia include ANO3 (DYT24), TUBB4A (DYT4), GCH1 (DYT5a), TH (DYT5b), TAF1 (DYT3), PRKRA (DYT16), ATP1A3 (DYT12), SGCE (DYT11), KCTD17, and CACNA1A." (PMID 33051750, 2021). "Consistent with its essential role in dopamine homeostasis, homozygous missense mutations in TH have been associated with dopamine-related phenotypes, such as Segawa's syndrome, L-DOPA responsive infantile parkinsonism, and L-DOPA responsive dystonia (DRD)." (PMID 20809526, 2010). "We also describe a previously not reported variant of the TH gene in a child with severe, early-onset dystonia." (PMID 30894892, 2018). "Although possibly causative, a homozygous variant in the TH gene was not reported before in children with dopa-responsive dystonia." (PMID 30894892, 2018).
Dystonia (continued). "Mutations in some dystonia genes, such as THAP1 (DYT6), can cause both focal/segmental and generalized forms of the disease, while others (e.g., TH or GCH1) may even give rise to both isolated and combined dystonias." (PMID 28138320, 2016). "The genotypes with very low TH activity are at the edge of the DA cliff and, interestingly, these genotypes sometimes show a dystonia, involuntary muscle contractions that affect posture, brought about by low levels of extracellular DA that can be alleviated by levodopa." (PMID 26400419, 2015). "Missense variants of human TH are associated with a recessive neurometabolic disease with low levels of brain dopamine and noradrenaline, resulting in a variable clinical picture, from progressive brain encephalopathy to adolescent onset DOPA‐responsive dystonia (DRD)." (PMID 30411798, 2019). "Quantification of TH-stained nigral neurons was obtained a mean of 53 days following MPTP, in all cases acute transient dystonia resolved." (PMID 37711667, 2023). "Chorea was also a prominent HMD in seven children with neurotransmitter defects (DDC, TH, SLC6A3), commonly in tandem with dystonia (n = 5), ballismus (n = 2), myoclonus (n = 1), coarse tremor (n = 3), and stereotypies (n = 1)." (PMID 36054588, 2022). "Of note, for several established dystonia genes, no carrier of a disease‐causing variant was identified in our large patient group (e.g., in AOPEP, HPCA, PRKRA, and TH)." (PMID 40533913, 2025). "One of the most interesting is the deletion of the entire TH (Tyrosine hydroxylase) gene, detected in a PD patient without evidence for dystonia but responsive to L-DOPA treatment, and in none of the controls." (PMID 27896429, 2017). "GAD67 and TH levels were comparable between control and DYT1 dystonia subjects." (PMID 26052670, 2015). "Notably, human GTPCH and TH are defective in two forms of dopa-responsive dystonia (DYT14 and DYT5, respectively), while torsinA is altered in DYT1 dystonia." (PMID 22022556, 2011).
pheochromocytoma (30 papers, 2011 to 2026). "α-MT is an orally active competitive TH inhibitor, which has been used to control hypertensive symptoms in pheochromocytoma patients." (PMID 36409355, 2022). "The best known and perhaps most commonly used marker for pheochromocytomas is tyrosine hydroxylase, an important enzyme in the synthesis of catecholamines." (PMID 36178902, 2022). "Extrinsic as well as intrinsic hypoxia led to an up-regulation of total catecholamine contents of different pheochromocytoma cell lines with a cluster 2-like phenotype presumably reflecting increased phosphorylation of TH." (PMID 31035382, 2019). "The cellular catecholamine contents of pheochromocytoma cells in response to hypoxia seem to be primarily regulated through an increased phosphorylation of TH at Ser40." (PMID 31035382, 2019). "Staining for tyrosine hydroxylase is, therefore, a convenient and reliable method to confirm the diagnosis of almost all PGLs and pheochromocytomas." (PMID 30217041, 2018). "In an in vitro model of NE-treated phaeochromocytoma cells, desipramine abolished reduction of tyrosine hydroxylase, the rate-limiting enzyme of NE synthesis and NE-induced cell death." (PMID 28420138, 2017). "Immunohistochemical staining for TH, the rate-limiting enzyme in the biosynthesis of catecholamines, was used as a marker of pheochromocytoma cells to discriminate tumor from cells of the tumor microenvironment." (PMID 23457505, 2013). "Denatured tyrosine hydroxylase from rat pheochromocytoma (denatured by sodium dodecyl sulfate)." (PMID 40177299, 2025). "For example, enzymes involved in catecholamines synthesis (Tyrosine Hydroxylase (TH), Dopamine-β-Hydroxylase (DBH), DOPA decarboxylase (DCC)) are overexpressed in pheochromocytoma." (PMID 40666287, 2025). "For immunohistochemistry analysis, positivity for tyrosine hydroxylase and GATA3 confirmed the diagnosis of pheochromocytoma." (PMID 35304467, 2022). "It has been discovered that pheochromocytomas contain significant amounts mRNA for the AADC, DBH and TH enzymes." (PMID 35186079, 2022). "A polyclonal antibody made against TH (498 aa; GenBank: AAA42258.1) from rat pheochromocytoma was used for detection." (PMID 26564062, 2015). "PC12 is a pheochromocytoma cell line able to synthesize catecholamines, whereas primary midbrain culture is a mixed population consisting of glia and MAP+ neurons, including TH+ immunopositive dopaminergic neurons." (PMID 21542899, 2011). "Although the tumor was unexpectedly negative for immunolabeling to tyrosine hydroxylase and synaptophysin, 25 and 15% of pheochromocytoma cases, respectively, can stain negative for these immunohistochemical markers." (PMID 41321567, 2025). "We then compared the results with pheochromocytoma of the adrenal gland scaled score (PASS), grading system for pheochromocytoma and paraganglioma (GAPP) and the status of intra-tumoral catecholamine-synthesizing enzymes (TH, DDC, and PNMT) as well as their clinicopathological factors." (PMID 33244312, 2020).
diabetes (24 papers, 2008 to 2026). "A further variant with significant association with TG in participants with diabetes mapped to the tyrosine hydroxylase (TH) gene, coding an enzyme that catalyzes the first step in the synthesis of catecholamines, such as dopamine and noradrenaline." (PMID 39258111, 2024). "Increases in immunostaining and mRNA expression for tyrosine hydroxylase in corpus cavernosum have been associated with sympathetic hyperactivity in diabetes and aging." (PMID 27935981, 2016). "In the glycyrrhizin-fed diabetic rats, the decrease in synaptophysin, tyrosine hydroxylase, and glyoxalase 1 caused by diabetes was significantly attenuated." (PMID 24733965, 2014). "Consistent with previous findings, histological analysis of the femurs from db/db mice at 4 months after the establishment of diabetes revealed significant reductions in the numbers of tyrosine hydroxylase-positive (Try-OH+) nerves." (PMID 35966130, 2022). "For example, streptozotocin affects the proteins encoded by TH and SULT1A2, and has been widely used experimentally to induce diabetes in rodent models due to its toxic effects on pancreatic beta cells." (PMID 34230558, 2021). "For instance, in experimental diabetes decreased TH activity in terminal fields for noradrenergic and dopaminergic neurons has been observed and genetically diabetic Wistar rats show decreased immunoreactive TH." (PMID 31474827, 2019). "Specifically, PFB supplementation increased the expression of TH in the striatum of diabetes-resistant NGR rats 3-fold (p < 0.005) and 2.4-fold (p < 0.003) in diabetes-susceptible rats via Student’s t-test." (PMID 31819070, 2019). "Diabetes-induced neuropathy was observed in intrapineal nerve fibres containing tyrosine hydroxylase in rats with streptozotocin-induced diabetes." (PMID 30304775, 2018). "We examined all the TH variants for potential link to relevant human disease using the EBI GWAS catalog and generated enriched candidate gene lists for obesity, diabetes and metabolic syndrome." (PMID 27835940, 2016). "In the GA-fed diabetic rats, the decrease in synaptophysin, TH, GS, and GLO1 caused by diabetes was attenuated by about 58%, 55%, 79%, and 53%, respectively." (PMID 24733965, 2014). "On the other hand, diabetes induced significant downregulation of synaptophysin, TH, GS, and GLO1 in the retinas of rats." (PMID 24733965, 2014). "Our findings concerning tyrosine hydroxylase provide evidence that supports the use of sympathomimetics to activate BAT in the treatment of diabetes, obesity, and other cardiometabolic disorders, as they illustrate the importance of innervation in the functionality of brown adipose tissue." (PMID 36714241, 2023). "Similarly, reduced TH activity in terminal fields for noradrenergic and dopaminergic neurons was observed in experimental diabetes, while genetically diabetic Wistar rats feature decreased levels of immunoreactive TH, too." (PMID 34830246, 2021). "However fasting plasma L-DOPA levels were markedly lower in T2D subjects, accompanied by a higher plasma tyrosine/L-DOPA ratio suggesting reduced activity of tyrosine hydroxylase in diabetes." (PMID 32589682, 2020). "Also, pharmacological studies have shown that the experimentally induced diabetes decreases the tyrosine and tyrosine hydroxylase levels in the brain." (PMID 34466420, 2018). "Importantly, diabetes increases labeling for TH-IR in the nerve plexus of PMAs." (PMID 24847201, 2014). "Western blot analysis was used to assess the effect of GA on diabetes-induced alterations of HMGB1, ERK1/2 activation, cleaved caspase-3, synaptophysin, TH, GS, and GLO1." (PMID 24733965, 2014). "The HMGB1 inhibitor GA attenuated diabetes-induced upregulation of HMGB1 protein and mRNA; cleaved caspase-3 and glutamate; and downregulation of synaptophysin, TH, GS, and GLO1 in the retinas of rats." (PMID 24733965, 2014). "The presence or absence of diabetes [high blood glucose] did not appear to affect tyrosine hydroxylase expression." (PMID 31819070, 2019).